CNP (2',3'-cyclic nucleotide 3' phosphodiesterase)
Diseases named in the same sentence as CNP in open-access papers (continued):
Sharing a sentence is not in itself a finding about the gene and the disease.
diabetes (3 papers, 2022 to 2025). "Taking these results together, the CNP/CPT-Metf was demonstrated to be able of significantly alleviating the type 2 diabetes mellitus in diabetic mice." (PMID 35411835, 2022). "Furthermore, it was demonstrated as well that CNP/CPT-Metf was able of significantly alleviating the type 2 diabetes mellitus in diabetic mice." (PMID 35411835, 2022). "Furthermore, CNP expression was decreased in both patients with and without diabetes, whereas the expression of PDE2 was clearly upregulated in DCM and DiabDCM." (PMID 40965622, 2025).
hepatoma (3 papers, 2013 to 2019). "It has also been demonstrated that CnP inhibits TGF-β-induced apoptosis in rat hepatoma cells, and, consistently, we showed that CnP significantly decreased hepatic TGF-β mRNA levels, along with those of MCP-1 and TIMP-1." (PMID 28594915, 2017). "To evaluate the CNP expression and its response to interferon in the hepatoma cell lines, we analyzed its mRNA and protein status in Huh7 and HepG2 cells." (PMID 24260477, 2013). "In this study, we evaluated expressions of CNP isoforms in hepatoma cell lines and their effects on HBV replication." (PMID 24260477, 2013). "It has been demonstrated that CnP inhibits TGF-β-induced apoptosis in rat hepatoma cells." (PMID 30689650, 2019). "It is unknown whether physiological expression or interferon induced CNP in hepatoma cell lines inhibits HBV replication." (PMID 24260477, 2013). "In this study, we investigate CNP expression in hepatoma cell lines and liver specimens, and determine whether the CNP modulates the HBV life cycle." (PMID 24260477, 2013). "Firstly, we detected the expression of CNP isoforms in hepatoma cell lines." (PMID 24260477, 2013).
Hypertension (3 papers, 2018 to 2021). The presence of chronic increased pressure in the systemic arterial system. "Recent studies found that LCZ696 increased local BNP/CNP levels, interfered with angiotensin II-mediated signaling, and then reduced the magnitude of cardiac remodeling in animal models of hypertension and myocardial infarction." (PMID 33928085, 2021). "This is in line with the findings that polymorphism of the CNP gene was an independent predictor of development of hypertension in a Japanese population but plasma CNP was not increased in hypertensive subjects compared with normotensive controls." (PMID 29506482, 2018).
myocardial infarction (3 papers, 2019 to 2023). Gross necrosis of the myocardium, as a result of interruption of the blood supply to the area, as in coronary thrombosis. "Infusion of CNP in myocardial infarction (MI)‐induced rats increased LV dP/dtmax and fractional shortening, whereas LVEDP and LV dP/dtmin were decreased compared to the MI‐vehicle group, suggesting both positive inotropic and lusitropic effects of CNP." (PMID 37493451, 2023).
oligodendroglioma (3 papers, 2013 to 2022). A well-differentiated (WHO grade II), diffusely infiltrating neuroglial tumor, typically located in the cerebral hemispheres. "All of these tumors arose from oligodendroglioma and in four of these a DNA methylation derived CNP was available showing complete 1p/19q codeletion in the primary tumor." (PMID 34967922, 2022).
acute kidney failure (2 papers, 2021 to 2025). "For acute kidney injury (AKI), the findings were 1.24 (0.89–1.73) for ABCP, 1.16 (0.37–3.60) for A + CnP, and 1.76 (1.06–2.93) for A + CbP." (PMID 41353554, 2025).
chronic hepatitis B (2 papers, 2013 to 2021). "In patients with chronic hepatitis B, CNP is expressed in most hepatocytes of HBV-infected liver specimens." (PMID 33441627, 2021). "In chronic hepatitis B patients, CNP was expressed in most of HBV-infected hepatocytes of liver specimens." (PMID 24260477, 2013).
dementia (2 papers, 2016 to 2017). Loss of intellectual abilities interfering with an individual's social and occupational functions. "Several dementia-specific citrulline residues were also identified in soluble proteins previously categorized as pro-immunogenic, which include the receptor P2X7, alpha-internexin, GFAP, CNP, MBP, and histones." (PMID 28865468, 2017).
dwarfism (2 papers, 2013 to 2022). "CNP knockout leads to severe dwarfism, and there has been important research into the role of CNP in the osteochondral system." (PMID 36101368, 2022). "As global CNP knockout mice (CNP KO) reportedly showed severe dwarfism, due to the impairment of endochondral ossification, research into CNPs has been preceded by studies on their role in the osteochondral system." (PMID 36101368, 2022).
fucosidosis (2 papers, 2015 to 2023). "A detailed examination of OL status in a canine model of fucosidosis identified significant OL loss in the corpus callosum and cerebellar white matter, which stabilized by 16 weeks of age, as visualized by decreased CNP, MAG, MAL and PLP1 expression, and reduced CNP and increased CASP6 staining." (PMID 37183607, 2023).
Hepatic fibrosis (2 papers, 2017 to 2019). The presence of excessive fibrous connective tissue in the liver. "Conophylline (CnP), a vinca alkaloid extracted from the leaves of the tropical plant Tabernaemontana divaricate, attenuates hepatic fibrosis in mice." (PMID 30689650, 2019). "Conophylline (CnP), a vinca alkaloid extracted from the leaves of the tropical plant Ervatamia microphylla, attenuates hepatic fibrosis in mice." (PMID 28594915, 2017). "With regards to the hepatobilliary system, CnP suppresses hepatic stellate cells and attenuates experimental hepatic fibrosis in rats; however, it remains to be elucidated whether CnP attenuates steatohepatitis in mice." (PMID 28594915, 2017).
Hepatic steatosis (2 papers, 2017 to 2019). Steatosis is a term used to denote lipid accumulation within hepatocytes. "Hematoxylin-eosin staining showed that HFD increases hepatic steatosis, which is attenuated by CnP treatment." (PMID 30689650, 2019). "We demonstrated that administration of CnP reduced HFD-induced hepatic steatosis that was measured as hepatic TG contents." (PMID 30689650, 2019). "CnP significantly attenuated the MCD-induced increases in hepatic steatosis, as well as hepatic inflammation and fibrosis." (PMID 28594915, 2017). "We demonstrated that administration of CnP attenuated MCD-induced hepatic steatosis as well as hepatic TG and FFA contents." (PMID 28594915, 2017). "Hematoxylin-eosin staining showed that the MCD diet obviously increased hepatic steatosis, which was attenuated by CnP." (PMID 28594915, 2017). "CnP dose-dependently attenuated the high-fat diet-induced hepatic steatosis." (PMID 30689650, 2019). "However, little is known about the CnP mediated inhibition of hepatic steatosis in high-fat diet-induced non-alcoholic fatty liver disease (NAFLD) mouse models." (PMID 30689650, 2019). "In the current study, we investigated whether CnP inhibits HFD-induced hepatic steatosis in a NAFLD mouse model." (PMID 30689650, 2019). "In the present study, we examined whether CnP decreases hepatic steatosis, inflammation, and fibrosis in db/db mice fed an MCD diet." (PMID 28594915, 2017). "In the current study, we investigated whether CnP inhibits MCD-induced hepatic steatosis, inflammation, and fibrosis in a NASH model." (PMID 28594915, 2017). "CnP could accordingly be considered as a therapeutic option to prevent hepatic steatosis in NAFLD." (PMID 30689650, 2019). "Next, we examined whether CnP-induced inhibition of hepatic steatosis was involved in autophagy." (PMID 30689650, 2019). "The results of this study indicate that CnP inhibits steatohepatitis, possibly through the inhibition of hepatic TGF-β mRNA levels, and induces an increase in PPARα mRNA levels, resulting in the attenuation of hepatic steatosis, inflammation, and fibrosis in mice." (PMID 28594915, 2017).
hypomyelinating leukodystrophies (2 papers, 2020 to 2024). "Mutations affecting genes that encode classical myelin proteins including PLP, CNP, MAG, TUBB4, and ASPA cause severe neurological disorders including hypomyelinating leukodystrophies (HLD) and spastic paraplegias (SPG)." (PMID 32973451, 2020).
Intellectual disability (2 papers, 2023 to 2025). "CircRNA fragile mental retardation 2 targeted the miR-650/2′,3′-cyclic nucleotide 3′-phosphodiesterase (CNP) pathway to increase RAFLS proliferation and inflammatory response, as revealed by an in vitro cell model assay." (PMID 37149637, 2023).
leukemia (2 papers, 2022 to 2026). A malignant (clonal) hematologic disorder, involving hematopoietic stem cells and characterized by the presence of primitive or atypical myeloid or lymphoid cells in the bone marrow and the blood. "High expressions of NT5C3B, MYC, and CNP were also able to differentiate between the non-leukemia and MRD-positive groups, while only MYC could distinguish between MRD-negative and MRD-positive groups." (PMID 41596324, 2026). "Statistically significant differences between the leukemia and MRD-negative groups were achieved by JUP, NT5C3B, MYC, GATA3, PTK7, CNP, SNAI1, and ICOSLG." (PMID 41596324, 2026). "High expression of JUP, NT5C3B, MYC, GATA3, PTK7, CNP, and ICOSLG clearly differentiated the leukemia from the non-leukemia group." (PMID 41596324, 2026). "Importantly, JUP, NT5C3B, MYC, and GATA3, PTK7, CNP, and ICOSLG differentiated both non-pathological conditions (non-leukemia and MRD-negative) from leukemia samples." (PMID 41596324, 2026). "Although we focused on showing genes whose high expressions had poor prognoses in leukemia, it is important to mention that these results were consistent with our findings in B-ALL, since high CNP expression correlated with better overall survival (data not shown)." (PMID 36428851, 2022).
Myocardial fibrosis (2 papers, 2024 to 2025). "The significant univariate association of CNP (inverse), and of ANP, BNP and cGMP (all positive), with E/A ratio in females possibly relates to CNP’s adaptive response to impaired diastolic function resulting from myocardial fibrosis as reported recently in female mice." (PMID 38689031, 2024).
non-alcoholic steatohepatitis (2 papers, 2017 to 2019). "We have previously shown that CnP inhibits non-alcoholic steatohepatitis (NASH) using a methionine-choline-deficient (MCD) diet-fed mouse model." (PMID 30689650, 2019). "However, little is known about whether CnP inhibits steatosis, inflammation, and fibrosis in non-alcoholic steatohepatitis (NASH) in mice." (PMID 28594915, 2017).
Obesity (2 papers, 2017 to 2020). Accumulation of substantial excess body fat. "Together these findings suggest that the overexpression of CNP in endothelial cells reduced the increase in the MesWAT–body weight ratio during HFD-induced obesity accompanying both reducing adipocyte size and modulating adipokines." (PMID 28852070, 2017). "Our findings indicate an important role for the CNP produced by the endothelial cells in the regulation of MesWAT hypertrophy, insulin resistance, and inflammation during high-fat diet–induced obesity." (PMID 28852070, 2017). "In this study, we examined the effects of CNP overexpression in the endothelial cells of mice with HFD-induced (E-CNP) or genetic (OBEC) obesity." (PMID 28852070, 2017). "We then sought to confirm the effects of endothelialcell–specific CNP overexpression in another obesity model." (PMID 28852070, 2017). "Therefore, we examined the role of endothelial cell–specific overexpression of CNP in HFD-induced obesity." (PMID 28852070, 2017). "We therefore hypothesized that endothelial cell–specific CNP overexpression may protect against the development of the obesity condition." (PMID 28852070, 2017). "In addition, the overexpression of CNP in endothelial cells ameliorated HFD-induced and genetic obesity-associated inflammation." (PMID 28852070, 2017). "Interestingly, our results revealed beneficial effects of endothelial cell–specific overexpression of CNP in the liver of mice with HFD-induced obesity." (PMID 28852070, 2017). "Furthermore, CNP overexpression improved glucose tolerance, decreased insulin resistance, and inhibited macrophage infiltration in MesWAT, thus suppressing pro-inflammation during high-fat diet–induced obesity." (PMID 28852070, 2017). "We found that CNP overexpression increased energy expenditure, reduced mesenteric adipose tissue (MesWAT) hypertrophy, and improved insulin sensitivity and hepatic lipid metabolism during HFD-induced obesity." (PMID 28852070, 2017). "Regardless of the type of obesity involved, we surmise that endothelial cell–specific overexpression of CNP reduces inflammation." (PMID 28852070, 2017). "Therefore, endothelial cell–specific CNP overexpression, which was increased in highly vascularized tissues such as BAT55, MesWAT56, and liver of our Tg mice, may protect against metabolic disorders in HFD-induced obesity." (PMID 28852070, 2017).
steatosis (2 papers, 2017 to 2019). Increased lipid within the cytoplasm of cells. "We demonstrated that CnP improves steatosis in mice through the upregulation of PPARA and its downstream targets involved in fatty acid oxidation and autophagy." (PMID 30689650, 2019). "In conclusion, the data obtained in the present study suggest that CnP attenuates steatosis through the stimulation of PPARA, CPT1, and CPT2-related β-oxidation in the liver." (PMID 30689650, 2019). "Therefore, CnP-induced attenuation of TGF-β signaling might reduce steatosis and inflammation signaling." (PMID 30689650, 2019). "The MCD diet also significantly increased hepatic TG contents, steatosis scores, and hepatic FFA contents, which were significantly decreased by CnP." (PMID 28594915, 2017).
brachydactyly (1 paper, 2018). A disease characterized by the presence of brachydactyly, including syndromic and non-syndromic forms. "As the humans with heterozygous CNP mutations reportedly had brachydactyly, we also investigated the lengths of bones in paw." (PMID 30235256, 2018).
brainstem infarctions (1 paper, 2022). "We found that about one fifth of CNP III were caused by brainstem infarctions, for which a MRI was essential." (PMID 34537871, 2022). "CNP III was caused more often by brainstem infarctions than CNP IV (p = 0.659) and VI (p = 0.0004)." (PMID 34537871, 2022). "It was a major difference to the literature that we were able to identify a high number of brainstem infarctions, especially for CNP III (19.7%)." (PMID 34537871, 2022). "The frequency of brainstem infarctions was somewhat higher in CNP III (19.7%) than in the other OMNPs." (PMID 34537871, 2022). "Only 7.1% of CNP VI were assigned to brainstem infarctions (p = 0.0004)." (PMID 34537871, 2022).
breast carcinoma (1 paper, 2022). "Importantly, the excellent breast cancer cells targeting ability of CNP/CPT-Metf, resulted in strong capacity of anti-proliferation and cell apoptosis inducing." (PMID 35411835, 2022).
Brugada syndrome (1 paper, 2025). A genetically heterogeneous condition characterized by complete or incomplete right bundle branch block accompanied by ST elevation in leads V1-V3. "This study is the first to analyze CNP expression and its specific receptors using ddPCR technology, showing for the first time their presence and activation in individuals with Brugada syndrome and offering insights into the potential role of the CNP system in BrS." (PMID 40563432, 2025).
chondrodysplasia (1 paper, 2025). "Recently, vosolitide, a human CNP analog, has been approved in Japan for the treatment of patients with chondrodysplasia and is being applied clinically." (PMID 39845482, 2025).
cognition (1 paper, 2020). Intellectual or mental process whereby an organism becomes aware of or obtains knowledge. "Reduction of CNP in EP4 antagonist‐elicited MSC EVs/exosomes decreased the therapeutic potential of the MSC GWEVs/exosomes for hippocampal damaged mice with these memory and cognition deficiencies." (PMID 31943851, 2020).
cognitive deficits (1 paper, 2017). "In particular, preventing or reversing the dysregulation of key OL driver genes such as CNP and downstream targets such as BIN1 deserve further research as interventions to help to alleviate the progression of cognitive deficits in AD." (PMID 29110684, 2017).
colitis (1 paper, 2025). Inflammation of the colon. "In colitis, the RORs were as follows: ABCP: 10.1 (7.61–13.3), A + CnP: 10.9 (4.54–26.4), A + CbP: 15.9 (10.7–23.9), with signals being detected in all regimens." (PMID 41353554, 2025).
Costello syndrome (1 paper, 2013). Costello syndrome (CS) is a rare multisystemic disorder characterized by failure to thrive, short stature, developmental delay or intellectual disability, joint laxity, soft skin, and distinctive facial features. "To mimic a severe form of Costello syndrome, we used a hemagglutinin (HA)-tagged CNP-HRasG12V mouse model (CNP-HRas)." (PMID 24035394, 2013).
cystic fibrosis (1 paper, 2014). Autosomal recessive disorder caused by pathogenic variants in the CFTR gene (cystic fibrosis transmembrane conductance regulator), which encodes a chloride and bicarbonate channel expressed in epithelial cells, and follow the diagnosis criteria. "Thibaut's team reasoned that during infection of cystic fibrosis patients, P. aeruginosa may be exposed to the lung hormone CNP (C-type natriuretic peptide)." (PMID 25070739, 2014).
fragile X syndrome (1 paper, 2018). A genetic syndrome caused by mutations in the FMR1 gene which is responsible for the expression of the fragile X mental retardation 1 protein. "Particularly, in a mouse model of fragile X syndrome, the cerebellum displays a transient reduction in MBP and 2’,3’-cyclic nucleotide 3’-phosphodiesterase (CNP) expression as well as myelination at PD7, later showing complete recovery at PD15." (PMID 30687009, 2018).
gastric cancer (1 paper, 2021). A primary or metastatic malignant neoplasm involving the stomach. "Novel polysaccharide-peptide complex such as CNP-1-2 would open a new avenue to combat cancers, including gastric cancer." (PMID 34135980, 2021). "CNP-1-2 displayed the strongest growth-inhibition effect on SGC-7901 human gastric cancer cells and was able to stimulate the activation of macrophages among all prepared polysaccharide fractions." (PMID 34135980, 2021).
Insulin resistance (1 paper, 2017). Increased resistance towards insulin, that is, diminished effectiveness of insulin in reducing blood glucose levels. "In conclusion, the overexpression CNP in endothelial cells promoted BAT thermogenesis, leading to increased energy expenditure and decreased MesWAT adipocyte hypertrophy, fatty liver, insulin resistance, and inflammation in HFD-fed Tg mice." (PMID 28852070, 2017).
malocclusion (1 paper, 2015). "A considerable proportion of total CNP knockout mice exhibit severe malocclusion, which may prevent normal eating; Col2a1–Cre; Nppcflox/flox mice also exhibit this phenotype." (PMID 26014585, 2015). "In addition, Col2a1–Cre; Npr2flox/flox mice also exhibited malocclusion just as observed in systemic or cartilage-specific CNP knockout mice." (PMID 26014585, 2015).
microcephaly (1 paper, 2017). A congenital or acquired developmental disorder in which the circumference of the head is smaller than normal for the person's age and sex. "Moreover, CNP-SCAP mice exhibit tremors and an unsteady gait after postnatal week 2, as well as microcephaly." (PMID 28549068, 2017).
oesophageal cancer (1 paper, 2017). "In this multivariate survival analysis on patients with oesophageal cancer, CNP 1 or 2 was shown to be related to a statistically worse overall survival (HR: 1.964 95% CI 1.371–2.814 p < 0.001)." (PMID 29196718, 2017).
pancreatic cancer (1 paper, 2022). "CnP has been demonstrated to have an antifibrotic effect in liver and pancreatic cancer; therefore, CnP becomes the target of CAF-depleting therapy." (PMID 35327514, 2022).